RNU6-218P (RNA, U6 small nuclear 218, pseudogene)
Gene: Small nuclear RNA gene on chromosome 7 (6,057,500 to 6,057,604, forward strand). Ensembl gene ENSG00000252929.
Homologues: Orthologues: chimpanzee U6 (98% identical), mouse Gm25039 (77% identical), guinea pig U6 (65% identical). Paralogues in human: RNU6-711P (85% identical), RNU6-1331P (84% identical), RNU6-384P (84% identical), RNU6-422P (84% identical), RNU6-1060P (83% identical), RNU6-11P (83% identical), RNU6-1209P (83% identical), RNU6-15P (83% identical), RNU6-189P (83% identical), RNU6-255P (83% identical), RNU6-30P (83% identical), RNU6-37P (83% identical), and 1287 more.